SIRT2 (sirtuin 2)
Diseases named in the same sentence as SIRT2 in open-access papers (continued):
Sharing a sentence is not in itself a finding about the gene and the disease.
cardiovascular diseases (13 papers, 2015 to 2025). "Remarkably, they found that the deacetylase SIRT2 was the sole protein exhibiting down-regulation during aging, and it was linked to both various cardiovascular diseases and epigenetic regulation." (PMID 39871888, 2024). "SIRT2 has been also proved to be associated with cardiovascular diseases." (PMID 35574497, 2022). "In this review, we summarized the different functions and simple mechanisms of SIRT2 in the cardiovascular system, which is expected to contribute to finding therapeutic targets for cardiovascular diseases." (PMID 34028177, 2021). "In short, SIRT2 provides a very promising idea for researchers to find drugs for treating cardiovascular diseases." (PMID 34028177, 2021). "Researches have shown that Sirt2 plays important roles in cardiovascular diseases." (PMID 40523615, 2025). "Future research may lead to interventions and treatments, such as SIRT2-enhanced gene therapies or SIRT2-specific agonists, with the potential to extend a healthy lifespan and address cardiovascular diseases." (PMID 39871888, 2024). "Due to the high prevalence of cardiovascular diseases in aging, several recent studies have also focused on studying whether SIRT2 could be playing an important role in the correct functioning of this system." (PMID 38132302, 2023). "Firstly, in contrast to that observed in the CNS, SIRT2 levels seem to be physiologically reduced with aging in the periphery, and its overexpression would be protective in the context of inflammation, vascular health, and cardiovascular diseases." (PMID 38132302, 2023). "Collectively, these studies have shown that SIRT2 is a cardioprotective deacetylase in cardiovascular disease and could be a therapeutic target for cardiovascular disease." (PMID 36101744, 2022). "Therefore, studies have increasingly been conducted to explore the relationship between SIRT2 and cardiovascular disease." (PMID 36101744, 2022). "In fact, SIRT2 plays a key and important role in cardiovascular diseases, and there are many aspects of the protein available for research, which is very useful for clarifying the future research direction and finding effective clinical drugs for treating cardiovascular diseases." (PMID 34028177, 2021). "At the same time, it can be seen that SIRT2 has a big difference in the impact of cardiovascular diseases, and sometimes the impact on the same disease is not even the same." (PMID 34028177, 2021).
peripheral neuropathy (5 papers, 2020 to 2023). A disorder affecting the peripheral nervous system. "Specifically, NAD+ administration increased intracellular ATP levels via the activation of SIRT2, which regulates Akt phosphorylation in BV2 microglial cells, while NR treatment alleviated cisplatin-induced peripheral neuropathy in a SIRT2-dependent manner." (PMID 38132442, 2023). "A role of SIRT2 in neuropathic pain has been highlighted in a mouse model of cisplatin-induced peripheral neuropathy (CIPN)." (PMID 35408848, 2022). "Knockdown of Sirt2 resulted in a deficiency in the LKB-1/AMPK/PGC-1α pathway and subsequent mitochondrial dysfunction and peripheral neuropathy in type 1 diabetic rodents." (PMID 32122297, 2020).
renal disease (4 papers, 2017 to 2025). "Of note, while Sirt1, Sirt2 and Sirt3 are involved in renal diseases, renal hypertrophy and fibrosis in mice deficient in these genes have not been reported." (PMID 28351995, 2017). "Preclinical models further suggest that SIRT2 has a complex and context-specific role in kidney disease." (PMID 41303131, 2025).
cerebral artery (2 papers, 2021 to 2022). "Similar findings indicate that SIRT2 is upregulated in ischemic neurons in the transient middle cerebral artery occlusion (tMCAO) mouse model and the oxygen-glucose deprivation cell model." (PMID 35574497, 2022). "To assess the relevance of hepatic SIRT2 expression to alcoholic liver injury, we analyzed SIRT2 protein expression in liver samples from normal controls (n = 12) and patients with ALD (n = 102) by immunohistochemical (IHC) staining." (PMID 34642310, 2021).
inflammation (2 papers, 2017 to 2020). Aberrant reaction of the microcirculation characterized by movement of fluid and leukocytes from the blood into extravascular tissues.
respiratory disease (2 papers, 2024 to 2025). "Several researches have been conducted on the association of respiratory disease pathophysiology and SIRT regulation; however, the molecular mechanisms of SIRT-2 involved in COPD remain unknown." (PMID 38979411, 2024).
psychiatric disorder (1 paper, 2023). A disorder characterized by behavioral and/or psychological abnormalities, often accompanied by physical symptoms. "Thus SIRT2 might serve as a potential treatment target for psychiatric disorders induced by manipulative parasites." (PMID 37721957, 2023).
SIRT2 also shares sentences with these, for which no sentence is quoted: Parkinson’s (12 papers); idiopathic pulmonary fibrosis (3); lipid metabolism disorders (3); acute myocardial infarction (2); astrocytoma (2); brain injury (2); Ciliopathies (2); COVID-19 (2); diffuse astrocytoma (2); diffuse large B-cell lymphoma (2); HIV-1 infection (2); metastatic tumors (2); osteoarthritis (2); thyroid cancer (2); adenovirus infection (1); adrenomyeloneuropathy (1); Alcohol Abuse and Alcoholism (1); alcoholic fatty liver disease (1); alcoholic hepatitis (1); anaplastic oligodendroglioma (1); autism spectrum disorder (1); autoimmune disease (1); bacterial pneumonia (1); benign prostatic hyperplasia (1); brain cancer (1); brain inflammation (1); Candidiasis (1); chronic periodontitis (1); clear cell renal carcinoma (1); coronary heart disease (1).
A further 52 diseases each share a sentence with SIRT2 in 1 paper.